MIR486-1 (microRNA 486-1)
Synonyms: hsa-mir-486; MIR486; MIRN486; hsa-mir-486-1; mir-486-1
Gene: MicroRNA gene on chromosome 8 (41,660,441 to 41,660,508, reverse strand). Ensembl gene ENSG00000274705.
Gene Ontology:
Biological process: miRNA-mediated post-transcriptional gene silencing
Cellular component: RISC complex
Homologues: Orthologues: chimpanzee ptr-mir-486 (100% identical), macaque MIR486-1 (100% identical), mouse Mir486 (88% identical), pig ssc-mir-486-2 (81% identical), rabbit MIR486-1 (78% identical), rat rno-mir-486 (76% identical), dog MIR486-1 (74% identical).